CGNL1 (cingulin like 1)
Description:
May be involved in anchoring the apical junctional complex, especially tight junctions, to actin-based cytoskeletons.
Synonyms: JACOP; KIAA1749; FLJ14957; PCING
Tractability: PROTAC: ubiquitination databases record sites on it; its protein half-life has been measured.
Gene: Protein-coding gene on chromosome 15 (57,375,967 to 57,550,729, forward strand). Ensembl gene ENSG00000128849.
Subcellular location: Cell junction, tight junction
Subcellular location (Human Protein Atlas): Cell Junctions; Nuclear bodies
Gene Ontology:
Molecular function: protein binding
Biological process: actin filament organization; negative regulation of small GTPase mediated signal transduction; negative regulation of stress fiber assembly; protein localization to cell-cell junction
Cellular component: cell junction; protein-containing complex; bicellular tight junction; actin cytoskeleton; apical junction complex; myosin complex
Genetic constraint (gnomAD): Loss-of-function variants: 115 observed, 123.58 expected, observed/expected ratio (o/e) 0.93, 90% interval 0.8 to 1.09. The upper end of that interval is the gene's LOEUF score, 1.09, which puts it in group 4 of 6, group 1 being the genes least tolerant of losing a copy. Missense variants: 1,716 observed, 1,532.5 expected, observed/expected ratio (o/e) 1.12, 90% interval 1.08 to 1.16. Synonymous variants: 636 observed, 608.03 expected, observed/expected ratio (o/e) 1.05, 90% interval 0.98 to 1.12.
Homologues: Orthologues: chimpanzee CGNL1 (99% identical), macaque CGNL1 (97% identical), dog CGNL1 (88% identical), pig CGNL1 (87% identical), rabbit CGNL1 (87% identical), mouse Cgnl1 (83% identical), rat Cgnl1 (82% identical), guinea pig CGNL1 (73% identical), tropical clawed frog cgnl1 (55% identical), zebrafish cgnl1 (47% identical). Paralogues in human: CGN (28% identical), MYH3 (18% identical), MYH7B (18% identical), MYH11 (17% identical), MYH4 (17% identical), MYH2 (17% identical), MYH13 (17% identical), MYH6 (17% identical), MYH7 (17% identical), MYH8 (17% identical), MYH10 (17% identical), MYH1 (16% identical), and 32 more.
Diseases named in the same sentence as CGNL1 in open-access papers:
CGNL1 is named in the same sentence as 22 diseases in open-access papers, as found by Europe PMC text mining. Sharing a sentence is not in itself a finding about the gene and the disease. The quoted sentences say what the papers report.
cyst (2 papers, 2024). A sac-like closed membranous structure that may be empty or contain fluid or amorphous material. "The KO of CGNL1 resulted in perturbed cyst morphogenesis for mCCD cells, and in a dramatic change of the organization of the PAN in Eph4 cells." (PMID 37013686, 2024). "Interestingly, although the Rod-1 region of CGNL1 was required to rescue the cyst morphogenesis phenotype, constructs comprising the Rod-1 region of CGN were also effective in rescuing the planar apical network of microtubules." (PMID 37013686, 2024). "The KO of CGNL1 results in disorganized cytoplasmic microtubules and irregular nuclei alignment in mouse intestinal epithelial cells, altered cyst morphogenesis in cultured kidney epithelial cells, and disrupted planar apical microtubules in mammary epithelial cells." (PMID 37013686, 2024). "This could be due to redundant functions of CGN and CGNL1, as CGNL1 controls cyst morphogenesis in mCCD cells, in which CGNL1 is abundantly expressed." (PMID 39319625, 2024).
osteosarcoma (2 papers, 2023 to 2024). A usually aggressive malignant bone-forming mesenchymal neoplasm, predominantly affecting adolescents and young adults. "Our qRT-PCR analysis demonstrated that osteosarcoma cells expressed higher levels of CGNL1 and CXCL13 compared to osteoblast cells, while ZNF583 had the opposite effect, indicating its potential as a novel anti-oncogene." (PMID 37980450, 2023). "Signature (ZNF583, CGNL1, CXCL13) was developed to predict overall survival in osteosarcoma patients, targeting the anoikis subcluster." (PMID 37980450, 2023). "The results revealed elevated levels of CGNL1 and CXCL13 in osteosarcoma cell lines, while ZNF583 was markedly downregulated." (PMID 37980450, 2023).
pneumonia (2 papers, 2022). An acute, acute and chronic, or chronic inflammation focally or diffusely affecting the lung parenchyma, caused by an infection in one or both of the lungs (by bacteria, viruses, fungi, or mycoplasma.). "Scaled PhIP-Seq examination of both MIS-C and KD demonstrated rare, overlapping antigens, including CGNL1, as well as several strongly enriched putative pneumonia-associated antigens in severe COVID19, including the endosomal protein EEA1." (PMID 35350199, 2022).
endometrial cancer (1 paper, 2020). Primary or metastatic malignant neoplasm involving the endometrium (mucous membrane that lines the endometrial cavity). "Previous studies demonstrated that CGNL1 gene expression is associated with endometrial cancer survival." (PMID 32292720, 2020).
endometrioid tumor (1 paper, 2019). A benign, borderline, or malignant epithelial tumor of the female reproductive system characterized by the presence of glands and/or cysts lined by neoplastic cells that resemble endometrial cells. "ANO1, SOX17, CGNL1, DACH1, RUNDC3B, SH3YL1 and CRISPLD1 were significantly downregulated both in papillary serous tumors and endometrioid tumor." (PMID 30813939, 2019).
lymph node metastasis (1 paper, 2020). "Our results showed that CGNL1 is a diagnostic factor for HGBC and can predict lymph node metastasis." (PMID 32292720, 2020). "According to clinicopathologic characteristics, we identified that CRYAB, ECM1, GPX3, and CGNL1 may predict histological grade, UICC stage and lymph node metastasis." (PMID 32292720, 2020).
oral cancer (1 paper, 2022). "The exact correlation between T cells regulatory and CGNL1 in the development of oral cancer has yet to be confirmed in future studies." (PMID 36626444, 2022).
prostate carcinoma (1 paper, 2018). A carcinoma that arises from epithelial cells of the prostate gland. "Five genes CGNL1, SUPV3L1, TATDN2, CASKIN1, and GOLGA7B are of unknown functions in either prostate cancer tumorigenesis or tumorigenesis in general." (PMID 30024105, 2018).
tumor (6 papers, 2015 to 2023). "CGNL1 in tumor tissues was significantly lower than that in adjacent tissues, and patients with high levels of CGNL1 have a better prognosis." (PMID 36626444, 2022). "Ultimately, we performed gene set enrichment analysis (GSEA), protein-protein interaction (PPI) networks, and Bayesian networks (BNs) to explore the underlying mechanisms by which ECM1, CRYAB, CGNL1, and GPX3 are involved in tumor progression." (PMID 32292720, 2020). "Seven genes (CACNB2, IL34, CGNL1, CNTN3, GAS7, HOPX, and PBX1) regulated by miR-31-5p and miR-31-3p were identified as putative tumor suppressors." (PMID 34201353, 2021). "Four genes, CAMK2N1, CGNL1, DLC1 and SYT11, the expression of which was lower in the tumor tissues than in the normal tissues, were enriched in the cell junction." (PMID 25789025, 2015). "CGNL1 correlates with several immune subsets, including resting CD4 memory T cells, follicular helper T cells, activated NK cells, and M2 macrophages, signifying its multifaceted role in shaping the tumor's immune landscape." (PMID 37980450, 2023).
cancer (4 papers, 2020 to 2023). A tumor composed of atypical neoplastic, often pleomorphic cells that invade other tissues. "Few detailed functional analyses of CGNL1 have been performed in cancer cells." (PMID 34201353, 2021). "Based on TCGA BLCA dataset, we found that CRYAB (AUC = 0.9326, P < 0.001), ECM1 (AUC = 0.6782, P = 0.009), CGNL1 (AUC = 0.9314, P < 0.001), and GPX3 (AUC = 0.8480, P < 0.001) are effective in distinguishing HGBC tissues and normal para-carcinoma tissues." (PMID 32292720, 2020). "CGNL1 and S100A8 are down-regulated in most cancers and up-regulated in a few cancers." (PMID 36626444, 2022).
cardiovascular disease (1 paper, 2022). "Although anti-CGNL1 antibodies were only found at low frequency, it is possible that these antibodies may represent a subset of specificities within anti-endothelial cell antibodies, given the endothelial expression of CGNL1 as well as its implications in cardiovascular disease." (PMID 36300623, 2022).
CGNL1 also shares sentences with these, for which no sentence is quoted: schizophrenia (2 papers); breast carcinoma (1); cervical squamous cell carcinoma (1); COVID-19 (1); diabetes (1); esophageal carcinoma (1); gastric cancer (1); head and neck cancer (1); lung squamous cell carcinoma (1); pancreatic cancer (1); squamous cell carcinoma (1).